EGFR (epidermal growth factor receptor)
Diseases named in the same sentence as EGFR in open-access papers (continued):
Sharing a sentence is not in itself a finding about the gene and the disease.
triple-negative breast carcinoma (continued). "One study has demonstrated that inhibition of FASN and EGFR increased the sensitivity to chemotherapy in triple-negative breast cancer." (PMID 39495391, 2024). "In clinical practice, Erlotinib, EGFR inhibitor, was efficient in patients with estrogen receptor-positive breast cancer; however, it had little effect on triple-negative breast cancer patients." (PMID 38239643, 2023). "To rule out the influence of endogenous receptors, we performed the experiment in the EGFR knockout SUM159 human triple-negative breast cancer cell line, which has very low HER2 expression." (PMID 36781849, 2023). "In line with these previous findings, we revealed that PELI1 acts as an E3 ubiquitin ligase of EGFR to enhance the recycling of EGFR, which accounts for its aberrant expression in triple-negative breast cancers." (PMID 36841821, 2023). "For example, high EGFR-expressed triple-negative breast cancer (TNBC) mice can be benefited from immunotherapy." (PMID 36522474, 2023). "In triple-negative breast cancer, picrasidine G has been found to reduce cancer cell proliferation by inhibiting the EGFR/STAT3 signaling pathway." (PMID 37686036, 2023). "In vivo experiments combining RT with epidermal growth factor receptor (EGFR)-targeted CAR T cells in triple-negative breast cancer demonstrated synergistic interaction of both modalities mediated via NF-kB-ICAM1 activation." (PMID 37173782, 2023). "The antibody anti-EGFR Cetuximab successfully targets EGFR-overexpressing cancers, specifically in triple-negative breast cancer." (PMID 37048731, 2023). "In the present study, we show that miR-218 and EGFR are inversely correlated in primary triple-negative breast cancer samples and cell lines." (PMID 37088795, 2023). "For instance, in triple-negative breast cancer treatment, hyaluronic acid–chitosan was built to deliver miR-34a mimics, and RNA-NPs (nanoparticles) decorated with EGFR-targeting aptamer, which was used to carry a miR-21 inhibitor." (PMID 36765782, 2023). "CD31 is a sensitive and specific marker for endothelial cells, EGFR is highly expressed in triple negative breast cancer cells (e.g., MDA-MB-231), and HER2 is highly expressed in BT474 cells." (PMID 36986815, 2023). "Cantharidin showed more suppressive effect on MDA-MB-231 and MDA-MB-468 cells, which are triple-negative breast cancer cells with high abundance of EGFR." (PMID 37670360, 2023). "In the present study, we aimed to characterize the relationship between miR-218 and the Epidermal Growth Factor Receptor (EGFR) as well as to understand downstream effects in triple-negative breast cancer (TNBC)." (PMID 37088795, 2023). "Epidermal growth factor receptor (EGFR) is overexpressed in approximately 50% of triple-negative breast cancer cases." (PMID 37048731, 2023). "In fact, CBD is known to inhibit EGF-induced activation of EGFR, proliferation, and chemotaxis in triple-negative breast cancer cells, including MDA-MB-231." (PMID 35806150, 2022). "Picrasidine N decreased cell viability by modulating the EGFR/STAT3 signaling pathway in EGFR-overexpressing triple-negative breast cancer cells." (PMID 35682782, 2022). "Recent research has shown that the sealed cell–cell adhesion structure promotes the accumulation of soluble factors such as epidermal growth factor receptor (EGFR) ligands at intercellular sites, whereby triple-negative breast cancer becomes malignant." (PMID 35606369, 2022). "A cell-type specific targeting of cancer cells with higher levels of EGFR was shown to be possible by coupling an anti-EGFR aptamer with anti-HOTAIR siRNA in a cell line model of triple-negative breast cancer (Wang YL." (PMID 35495157, 2022). "Reportedly, cetuximab, a chimeric EGFR-targeted monoclonal antibody, inhibited the proliferation of EGFR-overexpressing triple-negative breast cancer (TNBC) cells." (PMID 36387211, 2022).
triple-negative breast carcinoma (continued). "The combination of paclitaxel and piperine was found to improve the bioavailability of paclitaxel for triple-negative breast cancer by targeting epidermal growth factor receptor (EGFR)." (PMID 35127957, 2022). "Over-expression of epidermal growth factor receptor (EGFR) mainly in triple negative breast cancer is known to promote tumor survival and suppress apoptosis." (PMID 35517864, 2022). "The Kaur group is developing peptide-doxorubicin conjugates in order to treat triple-negative breast cancer (TNBC) by targeting cell-surface keratin-1 (K1) or epidermal growth factor receptor (EGFR) in cancer cells." (PMID 35631623, 2022). "Here, we assessed the effect of hypoxia (1% Oxygen) on the tumor suppressor Annexin A6 (AnxA6) and the response of triple-negative breast cancer (TNBC) cells to epidermal growth factor receptor (EGFR) and androgen receptor (AR) targeted therapies." (PMID 36230969, 2022). "Another study demonstrated that INPP4B depletion in triple negative breast cancer resulted in delayed EGFR trafficking from early endosomes to late endosomes/lysosomes." (PMID 35760104, 2022). "Aerobic glycolysis enhanced by EGFR signaling inhibits the efficacy of cytotoxic T cell in triple negative breast cancer cells." (PMID 36712687, 2022). "The EGFR/HER2 inhibitor varlitinib is used for the treatment of triple-negative breast cancer (TNBC), and its impact on LPS-induced neuroinflammation and the underlying mechanism of action have received little attention." (PMID 36341365, 2022). "While only a minimal response was induced by IFN-γ and TNF in triple-negative breast cancer cells, combined treatment with an epidermal growth factor receptor (EGFR) inhibitor was able to overcome these limitations." (PMID 35326515, 2022). "It was recently reported that PTK7 is involved in the activation of EGFR and Akt signaling in triple-negative breast cancer cells." (PMID 35216506, 2022). "Approximately half of the cases of triple-negative breast cancer and inflammatory breast cancer overexpress EGFR, but MCF7 cells, a model of hormone-positive breast cancer, are characterized as EGFRlow cells." (PMID 34884742, 2021). "MEL also reduced the activation of epidermal growth factor receptor (EGFR) in her2-enriched and triple-negative breast cancer." (PMID 34959710, 2021). "We made use of MDA-MB-231 cells, which are highly metastatic triple-negative breast cancer cells that express high levels of EGFR." (PMID 34680238, 2021). "It expresses EGFR on its surface, and resembles the Claudin-low subtype of triple-negative breast cancer (TNBC)." (PMID 35052426, 2021). "Various preclinical and clinical studies have also evaluated the effect of EGFR-TKIs in combination with other chemotherapeutic agents and therapies interfering with the proteins of downstream EGFR signaling in triple-negative breast cancer (TNBC)." (PMID 33918836, 2021). "The EGFR aptamer was bonded with the RNA tetrahedron structure to target triple-negative breast cancer cells." (PMID 34947679, 2021). "A similar result was seen in triple-negative breast cancer, where concomitant administration of the anti-androgen bicalutamide with an EGFR inhibitor had an anti-proliferative effect." (PMID 34681618, 2021). "One cellular study revealed that EGFR–integrin αvβ3 complex impairment repressed VM in triple-negative breast cancer." (PMID 34568026, 2021). "Cetuximab resistance is the main obstacle for the treatment of EGFR overexpression cancer, including triple-negative breast cancer (TNBC)." (PMID 33472170, 2021). "EGFR is overexpressed in up to 76% and amplified in up to 24% of triple-negative breast cancers (TNBC) cases and is correlated with a higher rate of recurrence, metastasis, and lower survival." (PMID 34203351, 2021). "EGFR signaling promotes aerobic glycolysis in triple-negative breast cancer (TNBC), and the inhibition of EGFR reverses the Warburg effect and reactivates oxidative phosphorylation (OXPHOS) in NSCLC cells." (PMID 34367462, 2021).
triple-negative breast carcinoma (continued). "In triple-negative breast cancers (TNBCs), IL-17 maintains activation of EGFR, thus promoting tumor growth and evasion of anti-EGFR therapies." (PMID 33794838, 2021). "A down regulated oncogenic protein HER2 and HER3 were observed in a HER2+ cell line with a reduction in the wild type epidermal growth factor receptor (EGFR or HER1) in a triple negative breast cancer cell line." (PMID 32784933, 2020). "NP-G2-044 treatment decreased the phosphorylation of ERK, PLCγ1, and PI3K downstream of EGF stimulation in EGFR-high triple-negative breast cancer cells." (PMID 32824026, 2020). "For instance, the non-canonical use of signaling cross-talk downstream of the EGF receptor sensitized resistant triple negative breast cancers to DNA-damaging chemotherapies by inhibition of EGFR." (PMID 32450888, 2020). "For example, the CL4 aptamer inhibits the growth of triple negative breast cancer (TNBC) cells by impairing binding of epidermal growth factor receptor (EGFR) to integrin αvβ3." (PMID 32848740, 2020). "In triple-negative breast cancer (TNBC), epidermal growth factor receptor (EGFR) overexpression is associated with increased metastatic potential and worst survival rates." (PMID 33050027, 2020). "We aimed to determine the role epidermal growth factor receptor (EGFR) plays in innate resistance to prexasertib in triple negative breast cancer (TNBC)." (PMID 35582228, 2020). "Knocking down epidermal growth factor receptor (EGFR) signaling in triple-negative breast cancer cells markedly increased their sensitivity to subsequent DOX treatment." (PMID 31938069, 2020). "Given that 10% of triple-negative breast cancers harbor BRCA1/2 mutations, our results support consideration of the PBD-containing EGFR-targeted ADC (ABBV-321) within this specific subset of EGFR-expressing TNBC." (PMID 33256808, 2020). "Animal trials in triple negative breast cancer model revealed that the RNA nanoparticles incorporated with anti-EGFR aptamer can specifically target tumor and significantly inhibit tumor growth after systemic injections." (PMID 32080195, 2020). "At least 50% of triple negative breast cancer (TNBC) overexpress the epidermal growth factor receptor, EGFR, which paved the way for clinical trials investigating its blockade." (PMID 32295603, 2020). "225Ac-nimotuzumab-SpyTag-∆N-SpyCatcher was effective in vitro and in an EGFR-positive triple negative breast cancer xenograft model." (PMID 33233524, 2020). "To understand the molecular mechanism of action by which NP-G2-044 decreases the growth of EGFR-high triple-negative breast cancer cells, we investigated the effect of NP-G2-044 on the signaling steps downstream of EGFR." (PMID 32824026, 2020). "The Window of Opportunity Trial utilizing dasatinib in operable triple negative breast cancers with nEGFR (NCT02720185) was conceptualized to determine if Src mitigation can prevent nuclear translocation of EGFR in stage I–III TNBC." (PMID 32295603, 2020). "In 2011, Irwin and colleagues reported that EGFR and c-Src co-localized into lipid rafts in triple negative breast cancer cells, and that this co-localization prompted cell sensitivity to simultaneous treatment with EGFR and c-Src inhibitors." (PMID 32517369, 2020). "Regarding triple-negative breast cancer, EGFR amplification has been reported to occur in approximately 60% of cases when analyzed by silver in situ hybridization, validating this receptor as a target in this malignancy." (PMID 32957689, 2020). "In this project, we decided to investigate cetuximab (CTX)-conjugated cubic gold nanocages (AuNCs) as model NPs for epidermal growth factor receptor (EGFR) targeting in triple-negative breast cancer (TNBC) cells." (PMID 36133537, 2019). "In triple-negative breast cancer cells, EGFR signaling regulates IGF2BP3 transcription since the IGF2BP3 promoter activity decreased after MEK1/2 signaling inhibition downstream of EGFR." (PMID 32010687, 2019).
triple-negative breast carcinoma (continued). "To assess the ability of new compounds to modulate EGFR expression and phosphorylation, we used the triple-negative breast cancer cell line MDA-MB-468, in which the receptor protein is overexpressed compared with the low expression of its counterpart ErbB2." (PMID 31374910, 2019). "BAG3 (BCL2-associated athanogene 3) knockdown is known to affect proliferation, migration, and invasion of EGFR-positive triple-negative breast cancer cell lines via AKT and FAK kinases." (PMID 31681584, 2019). "Unfortunately, drugs targeting EGFR activation such as gefitinib have limited clinical efficacy in cancers such as triple-negative breast cancer, in which up to 76% of cases overexpress EGFR49." (PMID 30796217, 2019). "EGFR/HER1 was predominantly expressed in the triple-negative breast cancer cell lines, MDA-MB-231 and MDA-MB-468, and a faint band was also detected in SK-BR-3." (PMID 30347895, 2018). "Previous work has suggested that through the Src-family kinase, Yes-1, EGFR amplifies FasL-induced cell migration in triple-negative breast cancer cells." (PMID 30127519, 2018). "It is important to identify novel drugs that can mediate EGFR pathway to inhibit cancer growth and metastasis, especially in triple negative breast cancer patients." (PMID 30618758, 2018). "Activation of epidermal growth factor receptor (EGFR) promoted the CSC phenotype with CD44+/CD24-expression, associated with invasiveness in triple-negative breast cancers." (PMID 29747682, 2018). "Taken together, retrograde trafficking of EGFR is responsible for driving migration in triple negative breast cancer, and its altered localization inhibits the effectiveness of the anti-EGFR antibody Cetuximab." (PMID 29464085, 2018). "It was also reported that PKM2 induces EGFR phosphorylation and activates downstream EGFR signalling in triple-negative breast cancer cells." (PMID 29127353, 2017). "Current EGFR-targeted therapy for triple negative breast cancer (TNBC) has produced disappointing results." (PMID 29156817, 2017). "This is in agreement with the notion of the crosstalk of EGFR with Notch signaling in triple negative breast cancer and their dual inhibition drastically attenuated active Akt(Ser473 )." (PMID 28270211, 2017). "Since EGFR is known to be in a crosstalk with Notch signaling in different tumor entities including triple negative breast cancer, we examined the effect of GSI on expression of EGFR transcript levels in control and Syndecan-1-depleted SUM-149 cells." (PMID 28270211, 2017). "Anti-EGFR monoclonal antibody combinations can enhance endocytic downregulation of EGFR, and these combinations showed superior anticancer efficacy in several human tumor xenograft models, including triple negative breast cancer and EGFR-mutant NSCLC." (PMID 28467975, 2017). "EGFR expression is elevated in up to 72% of basal and triple-negative breast cancers and correlates with poor prognosis in TNBC patients." (PMID 27655711, 2016). "We tested the efficacy of lapatinib, a dual tyrosine kinase inhibitor which interrupts the HER2 and epidermal growth factor receptor (EGFR) pathways, in a panel of triple-negative breast cancer (TNBC) cells, and examined the drug mechanism." (PMID 26824320, 2016). "More than 60% of triple-negative breast cancers (TNBC) overexpress EGFR and increased expression strongly correlates with cancer progression and negative outcomes." (PMID 27153091, 2016). "Triple-negative breast cancer (TNBC) is characterized by overexpression of epidermal growth factor receptor (EGFR) and activation of its downstream signaling pathways." (PMID 27655662, 2016).
triple-negative breast carcinoma (continued). "It has been demonstrated that the triple-negative breast cancer cell line (BT-20) is sensitive to sequential and time-dependent combinatorial drug treatments using the EGFR inhibitor Erlotinib and DNA damage inducer Doxorubicin15." (PMID 27774993, 2016). "Preclinical studies demonstrated 806-PE38 inhibition of the viability of triple-negative breast cancers, which commonly show amplification or overexpression of EGFR, at concentrations below 150 pM." (PMID 27153091, 2016). "Here, we report combined EGFR-ROCK inhibition as a potential combination treatment for triple-negative breast cancer." (PMID 27374095, 2016). "Overexpression of EGFR has been demonstrated in approximately half of cases of triple-negative breast cancer and inflammatory breast cancer." (PMID 27557521, 2016). "Co-inhibition of EGFR and ROCK in triple-negative breast cancer cells caused decrease in phosphorylated pRB, p27, Cyclin A and Cdk2 protein levels, correlating with an almost complete loss of the ability of the cells to replicate and consequently, proliferate." (PMID 27374095, 2016). "For the most part, in vivo studies indicate that phyto-, synthetic- and endo- cannabinoids suppress tumor development in hormone receptor positive, EGFR positive and triple negative breast cancer animal models." (PMID 27774065, 2016). "Triple-negative breast cancer (TNBC) exhibits innate resistance to the EGFR inhibition despite high level expression of EGFR." (PMID 25955731, 2015). "Signaling via epidermal growth factor receptor (EGFR) and Src kinase pathways promote triple-negative breast cancer (TNBC) cell invasion and tumor metastasis." (PMID 25823823, 2015). "Treatment of mesenchymal carcinoma cells with BGB324 abolished cell invasion and increased chemosensitivity, whilst it nullified the tumorigenic effect of triple negative breast cancer as well as blocking their acquired resistance to erlotinib (anti-EGFR SMI)." (PMID 25980499, 2015). "PEA-15 can also promote ER-anchored protein tyrosine phosphatase PTP1B functions to dephosphorylate EGFR in triple negative breast cancer (TNBC) cells, down-regulating EGFR signaling in cancer cells." (PMID 26263999, 2015). "In a recently published study, EGFR overexpression was useful in predicting response in patients with triple-negative breast cancer treated with neoadjuvant chemotherapy." (PMID 25216514, 2014). "Triple-negative breast cancers (TNBCs) are known to be intrinsically resistant to inhibitors for epidermal growth factor receptor (EGFR)." (PMID 23601074, 2013). "We also show that the wild type epidermal growth factor receptor (EGFR or HER1) declines in a triple negative breast cancer (TNBC) cell line in response to ADP NPs." (PMID 23516601, 2013). "The majority of the triple-negative breast cancer patients had a high expression of EGFR, VEGF and Ki 67 had a poor prognosis and shorter survival." (PMID 29147345, 2013). "The majority of triple-negative breast cancer tumors overexpress the EGFR(epidermal growth factor receptor)." (PMID 23039971, 2012). "Here we demonstrate that fibroblast secretion of HGF activates Met and leads to EGFR/Met crosstalk and resistance to EGFR TKIs in triple-negative breast cancer (TNBC)." (PMID 22788954, 2012). "In this study, we investigated the therapeutic effects of the nanobioconjugate carrying a combination of EGFR AON and 2C5 anti-tumor mAb along with TfR as active targeting for EGFR-positive triple negative breast cancer treatment." (PMID 22355336, 2012). "Epidermal growth factor receptor (EGFR) is expressed in triple negative breast cancer and several clinical trials are testing the role of anti-EGFR directed therapy." (PMID 21457545, 2011). "BRCA1-linked breast tumours typically exhibit triple negative expression (ER-/PR-/Her2-), express basal cytokeratins 5 and 6, and EGFR and show similar histopathological features to basal-like/triple negative breast cancers." (PMID 21457545, 2011).